IQCF5 (IQ motif containing F5)
Tractability: No criterion of Open Targets' tractability assessment is met for any kind of drug.
Gene: Protein-coding gene on chromosome 3 (51,873,721 to 51,875,601, reverse strand). Ensembl gene ENSG00000214681.
Gene Ontology:
Molecular function: calmodulin binding
Cellular component: acrosomal vesicle
Genetic constraint (gnomAD): Loss-of-function variants: 3 observed, 5.14 expected, observed/expected ratio (o/e) 0.58, 90% interval 0.26 to 1.47. That is too few expected variants to judge how well the gene tolerates losing a copy. Missense variants: 167 observed, 179.57 expected, observed/expected ratio (o/e) 0.93, 90% interval 0.82 to 1.06. Synonymous variants: 58 observed, 56.72 expected, observed/expected ratio (o/e) 1.02, 90% interval 0.83 to 1.27.
Homologues: Orthologues: chimpanzee IQCF5 (99% identical), macaque IQCF5 (91% identical), pig IQCF5 (78% identical), rabbit IQCF5 (77% identical), guinea pig IQCF5 (76% identical), mouse Iqcf5 (74% identical), rat Iqcf5 (74% identical), dog IQCF5 (71% identical). Paralogues in human: IQCF1 (58% identical), IQCF2 (45% identical), IQCF6 (42% identical), IQCF3 (39% identical).
Diseases named in the same sentence as IQCF5 in open-access papers:
IQCF5 is named in the same sentence as 1 disease in open-access papers, as found by Europe PMC text mining. Sharing a sentence is not in itself a finding about the gene and the disease.
IQCF5 shares sentences with these, for which no sentence is quoted: male infertility (1 paper).